DDIT4 (DNA damage inducible transcript 4)
Diseases named in the same sentence as DDIT4 in open-access papers (continued):
Sharing a sentence is not in itself a finding about the gene and the disease.
prostate carcinoma (21 papers, 2014 to 2025). A carcinoma that arises from epithelial cells of the prostate gland. "DDIT4 expression in prostate cancer was closely associated with PI3K-AKT-mTOR pathways node gene and EMT biomarker expression." (PMID 38384328, 2024). "Finally, the DDIT4 expression level was associated with bone metastasis in prostate cancer." (PMID 38384328, 2024). "An in-depth investigation was conducted into the functions of DDIT4 in the FTO-triggered EMT of prostate cancer cells, even though the promotion roles of FTO/TGF-β in EMT and prostate cancer development have been extensively established previously." (PMID 38384328, 2024). "Next, the interference of FTO expression in prostate cancer cells showed that the DDIT4 mRNA half-life was longer in cancer cells than in the wild-type cells, which indicated that m6A had a positive regulatory effect on mRNA stability." (PMID 38384328, 2024). "Subsequently, DDIT4 was closely associated with the expression of m1A, m5C, and m6A regulators pan-cancer, and DDIT4 was a target gene involved in multiple modifications in prostate cancer." (PMID 38384328, 2024). "IHC findings revealed that DDIT4 expression was decreased in prostate cancer, whereas AR expression was up-regulated." (PMID 38384328, 2024). "In a previous study, the m6A “eraser” FTO was shown to regulate the m6A modification level of the EMT target gene DDIT4 in prostate cancer." (PMID 38384328, 2024). "Western blot analysis used to determine protein expression demonstrated that si-IGF2BP2/3 inhibited the TGF-β-induced production of DDIT4 in prostate cancer cells." (PMID 38384328, 2024). "In gastric and prostate cancers, overexpression of DNA damage inducible transcript 4 (DDIT4) and the metallothionein MT1X have both been identified to associate with poorer prognosis and/or increased metastatic phenotypes." (PMID 35614362, 2022). "Therefore, western blotting was used to determine how DDIT4 affects the PI3K-Akt-mTOR signaling pathway during prostate cancer EMT." (PMID 38384328, 2024). "In addition, DDIT4 is a key effector of autophagy, thereby promoting prostate cancer resistance to proteasome inhibitors (bortezomib) by regulating the formation of autolysosomes." (PMID 38384328, 2024). "In addition, previous studies have shown that DDIT4 is significantly downregulated in prostate cancer cells and that the induction of DDIT4 expression can regulate MYC, which is a downstream target of the mTOR signaling pathway." (PMID 39697534, 2021). "Here we show that miR-101 targets other known players in prostate cancer DDIT4, STC1 and QK1." (PMID 27270442, 2016). "In addition to AMPK modulation, we also found that metformin treatment in human glioma cell induces a significant increase in Redd1/DDIT4 expression, as previously reported for prostate cancer cells." (PMID 25867026, 2015). "Moreover, DDIT4 can be suggested as a possible biomarker for prostate cancer metastasis prediction." (PMID 38384328, 2024). "Therefore, it was necessary to clarify whether DDIT4 affects prostate cancer development via the m6A pathway." (PMID 38384328, 2024). "In addition, DDIT4 expression could be induced by nicotinamide nucleotide transhydrogenase antisense RNA 1 (NNT-AS1)/miR-496 axis in prostate cancer and played a carcinogenic role in proliferation and migration." (PMID 36768316, 2023).
prostate carcinoma (continued). "An association was detected between m6A methylation and bone metastasis in prostate cancer, which showed that FTO knockout boosted DDIT4 expression and stimulated PC-3 cell invasion and EMT in vivo." (PMID 38384328, 2024). "DDIT4, identified as a novel EMT-related gene by Zhao, is regulated by m6A and plays a critical role in promoting EMT, motility, and invasive metastasis in prostate cancer cells." (PMID 38898043, 2024). "DDIT4, a target gene of EMT that is regulated by FTO, is involved in prostate cancer metastasis." (PMID 38384328, 2024). "Moreover, the measurement of the rate of RNA decay in prostate cancer cells with IGF2BP2/3 silencing and corresponding controls showed that the DDIT4 mRNA level was decreased and the mRNA half-life was significantly shortened after IGF2BP2/3 silencing in LNCaP cells." (PMID 38384328, 2024). "Therefore, DDIT4 may be involved in the m6A-regulated EMT invasion and migration of prostate cancer." (PMID 38384328, 2024).
ovarian carcinoma (17 papers, 2017 to 2025). A malignant neoplasm originating from the surface ovarian epithelium. "In addition, study found that AKT S473 activation was associated with over-expression of DDIT4 in ovarian cancer tissues." (PMID 30157901, 2018). "Additionally, DDIT4 expression was significantly increased in serous adenocarcinoma compared with other histological types, and this increase was positively associated with ascites formation and late-stage disease in ovarian cancer (OC)." (PMID 29976242, 2018). "While cytoplasmic overexpression of DDIT4 protein was shown in several studies to be a poor prognosis factor for tumor progression in ovarian carcinoma, acute myeloid leukemia, OSCC, and BUC22,28,33,65." (PMID 37938616, 2023). "DDIT4 correlated with tumor progression and affected the prognosis of patients with ovarian carcinoma." (PMID 34007269, 2021). "DNA-damage-inducible transcript 4 (DDIT4), also known as REDD1/Dig2/RTP801, was over-expressed in high-grade ovarian cancer and significantly linked with late stage cancer patients." (PMID 30157901, 2018). "We also demonstrate that the chromosomal locus containing the DDIT4 gene is directly associated with PML NBs, and that DDIT4 and PML expression levels are significantly correlated in several solid tumours including breast, lung and ovarian cancers." (PMID 28332630, 2017). "In addition, treatment with baicalein increased the expression of DDIT4 (a negative regulator of mTOR), enhanced AMPK phosphorylation, and reduced phosphorylation of downstream effectors S6K1 and S6, consistent with prior studies in breast and ovarian cancer." (PMID 41303544, 2025). "In contrast, a positive correlation between DDIT4 and p-AKT was identified in ovarian cancer (OC), and DDIT4 expression in OC tissues was significantly increased in patients with serous adenocarcinoma and late FIGO stage, indicating that DDIT4 might be a tumor promotor in OC." (PMID 29976242, 2018).
diabetes (16 papers, 2016 to 2025). "We recently demonstrated that the stress response protein regulated in development and DNA damage response 1 (REDD1, also known as DDIT4/RTP801) is necessary for diabetes-induced retinal inflammation and activation of canonical NF-κB signaling." (PMID 37392853, 2023). "1,25(OH)2D3 provides a potential benefit in the regulation of the mTOR signaling pathway by stimulating DNA-damage-inducible transcript (DDIT4) expression in the treatment of diabetes." (PMID 36820117, 2023). "By suppressing energy-intensive and ROS-generating pathways, DDIT4/REDD1 is vital for maintaining β-cell integrity and insulin secretory function during and after hypoxic episodes, such as those encountered in diabetes or during islet transplantation." (PMID 41440034, 2025). "The stress response protein REDD1 (Regulated in Development and DNA Damage 1; also known as DDIT4 or RTP801) is upregulated in the kidneys of diabetic patients, as well as in preclinical rodent models of diabetes." (PMID 39920111, 2025). "The paralogs DDIT4 and DDIT4L have been most extensively studied in skeletal muscle tissue, and DDIT4 has also received considerable attention relating to its role in cancer and diabetes." (PMID 38319716, 2024).
colorectal cancer (13 papers, 2019 to 2026). A primary or metastatic malignant neoplasm that affects the colon or rectum. "This study was conducted to investigate expression and prognostic significance of DDIT4 protein as a biomarker in the patients with colorectal cancer (CRC)." (PMID 34211002, 2021). "Contrary, upregulation of DDIT4 can stimulate cell proliferation in gastric epithelial cells and high expression of DDIT4 correlates with more aggressive tumour behaviour and more advanced stages of disease in colorectal cancer patients." (PMID 40871563, 2025). "In colorectal cancer, DDIT4 has been identified as an advanced stage and metastasis biomarker." (PMID 36768316, 2023). "Interestingly, REDD1/DDIT4 expression is upregulated in several tumor types including colorectal cancer, suggesting it may have a role in tumourigenesis." (PMID 41904147, 2026). "During glutaminolysis inhibition in colorectal cancer, activating transcription factor 4 (ATF4) is increased to reduce mTOR signaling by transcriptionally activating the mTOR suppressor DNA damage-inducible transcript 4 (DDIT4)." (PMID 36900220, 2023). "To investigate levels of DDIT4, we examined protein content in commonly used glioma cell lines as well as HEK293 cells and one colorectal carcinoma cell line (HT29)." (PMID 30745581, 2019).
lung adenocarcinoma (12 papers, 2017 to 2025). A carcinoma that arises from the lung and is characterized by the presence of malignant glandular epithelial cells. "Our results found that DDIT4 expression was upregulated in epithelial cells in brain metastases relative to epithelial cells in lung adenocarcinoma and was associated with poor prognosis." (PMID 37715019, 2023). "In our study, the upregulation of DDIT4 expression was associated with poorer OS in lung adenocarcinoma." (PMID 37715019, 2023). "To investigate the associations between DDIT4 protein expression and clinical outcomes, we examined specimens from 75 cases of lung adenocarcinoma by immunohistochemistry (IHC) using anti-DDIT4 staining." (PMID 34659532, 2021). "The study revealed that RRM2, SLC2A1, DDIT4, and VDAC2 were positively associated with the survival risk of lung adenocarcinoma patients." (PMID 39311766, 2024). "DDIT4 participates in the occurrence of tumors and affects the survival of patients, which adversely affects the survival of lung adenocarcinoma." (PMID 39311766, 2024). "Moreover, DDIT4 was identified to be an ideal molecule to classify patients with skin melanoma, and related to poor overall survival in lung adenocarcinoma patients." (PMID 36455876, 2022). "Statistical analysis revealed that DDIT4 was highly expressed in both lung adenocarcinoma and squamous cell carcinoma compared to noncancerous lung tissues (P < 0.001)." (PMID 34659532, 2021).
Obesity (12 papers, 2016 to 2025). Accumulation of substantial excess body fat. "DHA promotes mitochondrial biogenesis and skeletal muscle fiber remodeling via FTO/m6A/DDIT4/PGC1α signaling, protecting against obesity-induced decline in skeletal muscle function." (PMID 35135551, 2022). "Further analysis of the associated molecular mechanism revealed that DHA enhanced expression of the fat mass and obesity-associated gene (FTO), leading to reduced m6A levels of DNA damage-induced transcript 4 (Ddit4)." (PMID 35135551, 2022). "We concluded that the inhibition of miR-221-3p and miR-222-3p and DDIT4-mediated inhibition of mTORC1 signaling is one of the major mechanisms for the protection from diet-induced obesity." (PMID 35046889, 2021). "We demonstrated that the inhibition of miR-221-3p and miR-222-3p and subsequent DDIT4-mediated inhibition of mTORC1 signaling is a therapeutic target for the treatment of obesity." (PMID 35046889, 2021). "Interestingly, various obesity related factors have been shown to upregulate DDIT4, which may contribute towards the development of insulin resistance, and genetic inhibition of the DDIT4 gene has been observed to impair insulin sensitivity." (PMID 36662841, 2023). "Promotes obesity and NAFLD in mice via regulation of m6A‐modified DDIT4." (PMID 40066222, 2025). "In another study, loss of METTL3 leads to a reduction in the activity of mTOR and NF-κB signaling pathways, resulting from the stabilization of m6A-mediated DNA Damage Inducible Transcript 4 (DDIT4) mRNA in macrophages, which regulated metabolic reprogramming in NAFLD and obesity." (PMID 37227534, 2023).
depression (11 papers, 2018 to 2025). "In individuals with depression, DDIT4 is activated in the mouse prefrontal cortex (PFC) in response to stress." (PMID 40358153, 2025). "Among the 36 mRNAs associated with the ceRNA network, 3 mRNAs had been reported to be related to depression (DDIT4, S100B, Fbln2)." (PMID 35431783, 2022). "Interestingly, some of the linear dose-response DEGs have been implicated in transmission and plasticity (GRIN2A, GAD2), depression and antidepressant effect (DDIT4, GAD2) anxiety and stress responses (ADCYAP1R1), WNT signalling (FRZB), neurogenesis (ARHGEF39) and hippocampal volume (ANKRD37)." (PMID 39055655, 2024).
Atrophy (10 papers, 2015 to 2025). Any weakening or degeneration, especially through lack of use. "RNA sequencing identified shared dysregulated pathways, notably DDIT4 upregulation, linked to synaptic dysfunction and neuronal atrophy in animal models." (PMID 41153391, 2025). "DDIT4−/− mice are known to be resistant to a diverse set of stress conditions such as those caused by oxidative stress in the retina, tobacco smoke-induced emphysema, steroid-induced atrophy in the skin and apoptosis of lung epithelial cells caused by ceramide." (PMID 27898044, 2016).
glioblastoma (10 papers, 2017 to 2025). The most malignant astrocytic tumor (WHO grade IV). "SurvExpress platform had 9 glioblastoma datasets where DDIT4 overexpression was related with an increased risk of death in 2 out of 9 datasets (TCGA dataset for glioblastoma multiforme and GSE16011)." (PMID 28484222, 2017). "Interestingly, when we interrogated glioblastoma databases we found that elevated level of DDIT4 expression was associated with the longevity of glioma patients." (PMID 32153581, 2020). "DDIT4 was also connected to both autophagy and stemness, which were involved in temozolomide drug resistance and poor prognosis of glioblastoma multiforme patients." (PMID 34007269, 2021). "DDIT4 signaling was connected to both autophagy which were involved in temozolomide drug resistance and the poor prognoses of glioblastoma multiforme patients." (PMID 34007269, 2021). "Using short hairpin RNA-mediated gene suppression as well as doxycycline-regulated gene induction, we developed a glioblastoma cell model to study effects of DDIT4 under conditions of the glioblastoma microenvironment and therapy." (PMID 30745581, 2019). "Temozolomide and radiotherapy also induced DDIT4 and repressed mTORC1 activity in some glioblastoma cell lines." (PMID 30745581, 2019). "We found an intact DDIT4-mTORC1 signalling axis in human glioblastoma cells that was inducible by hypoxia." (PMID 30745581, 2019). "It has been reported that DDIT4 can mediate cellular adaptive therapy resistance in glioblastoma." (PMID 40621878, 2025). "Similarly, DDIT4 expression promoted the survival of glioblastoma cells by inhibiting mTORC1, which is a major mechanism contributing to anti-tumor therapy resistance." (PMID 37391802, 2023). "We identified DDIT4 as a cell-intrinsic regulator for adaptive responses and therapy resistance in glioblastoma cells which may interfere with cell death induction by temozolomide, radiotherapy or hypoxia by inhibiting mTORC1 activity." (PMID 30745581, 2019). "Notably, a recent study has identified that temozolomide and radiotherapy could induce DDIT4 and repressed mTORC1 activity in some glioblastoma cell lines." (PMID 32153581, 2020). "Thus, overexpression of DDIT4 by demeclocycline in BTIC could be beneficial for glioblastoma patients." (PMID 32153581, 2020).
glioma (10 papers, 2015 to 2024). A benign or malignant brain and spinal cord tumor that arises from glial cells (astrocytes, oligodendrocytes, ependymal cells). "In lower grade gliomas DDIT4 gene expression was associated with prolonged survival." (PMID 30745581, 2019). "ADM has been reported as one of 5 candidate genes associated with glioma resistance to TMZ, which showed to be consistently linked to higher expression of DDIT4 and lower prognosis in TMZ-treated cells." (PMID 36183123, 2022). "DDIT4 gene suppression sensitised glioma cells towards hypoxia-induced cell death, while DDIT4 overexpression protected them." (PMID 30745581, 2019). "Among these genes, DDIT4 activates the mTOR signaling pathway to promete the glioma progression." (PMID 35913967, 2022).